VCAM1 (vascular cell adhesion molecule 1)
Diseases named in the same sentence as VCAM1 in open-access papers (continued):
Sharing a sentence is not in itself a finding about the gene and the disease.
cancer (continued). "ICAM-1 and VCAM-1 are involved in cell-cell and cell-extracellular matrix (ECM) interactions, and they are mechanistically important for the extravasation of monocytes during inflammation and cancer cells during metastasis." (PMID 25156554, 2014). "To confirm the role of hydrogen peroxide and hydroxyl radical on cancer-endothelial cell interaction and to define the affected adhesion molecules, we blocked the endothelial surfaces with specific antibodies against VCAM-1, ICAM-1 and E-selectin, prior to cancer cell adhesion." (PMID 23460862, 2013). "Cancer cell-endothelial cell interaction is mediated by various adhesive molecules such as intracellular adhesion molecule-1 (ICAM-1), vascular cell adhesion molecule-1 (VCAM-1) and E-selectin." (PMID 23874773, 2013). "Low CXCL12 and VCAM1 has been related to both cancer progression and improved prognosis in various cancers, but no clear relation to chemo-resistance has been reported." (PMID 22905093, 2012). "Expression of VCAM-1 was detected in 11 (61%) of 18 SGC cases in which extensive growths of CAFs surrounded the cancer cells, and three (15%) of 17 non-SGC cases in which cancer cells had a tubular formation with desmoplastic change in CAFs." (PMID 19773759, 2009). "However, adhesion molecules such as intercellular adhesion molecule 1 (ICAM-1), vascular cell adhesion molecule 1 (VCAM-1), and selectins aid TILs in adhesion to epithelial cells and create a TME that favors the host cell in the fight against cancer-infiltrating cells." (PMID 40872475, 2025). "In addition, strong A4B1 interactions with FN1, VCAM1 and other ligands are seen with fibroblasts in P5-1, P6-1, and P7-1, and ESC in P6-1; A4B1 receptors have been proposed to target therapy in inflammatory disorders and cancer." (PMID 38328306, 2023). "Therefore, the correlation between CX3CL1 and ICAM‐1 or VCAM‐1 is explored in the present study, showing that only CX3CL1‐induced ICAM‐1 expression is observed, indicating that ICAM‐1 plays a vital role in CX3CL1‐induced cancer metastasis." (PMID 37082943, 2023). "Interestingly, even though VCAM-1 is established as a viable target in immunological disorders and cancer, no human or humanized mAb or low molecular weight (Mw) inhibitor is being tested in clinics." (PMID 35463298, 2022). "The role of pycnogenol in inhibiting NFκB activation, and vascular cell adhesion molecule 1 (VCAM-1) and intercellular adhesion molecule 1 (ICAM-1) expression suggests that this antioxidant compound may play a role in cancer prevention and atherogenic processes." (PMID 34205739, 2021). "cGAS-driven extracellular export of 2′3′ cGAMP by cancer cells activates STING signaling in endothelial cells and cooperates with type 1 interferon to increase vascular permeability and expression of E selectin, VCAM-1, and ICAM-1 and T cell adhesion to the endothelium." (PMID 33013881, 2020). "Furthermore, we observed that both the mRNA and protein levels of a collection of NF‐κB downstream effectors that are central co‐ordinators of cancer cell metastasis, such as ICAM1, VCAM1 and MMP9, were decreased by RPS15A knockdown, but increased by RPS15A overexpression." (PMID 30661291, 2019). "NF-κB signaling may also participate in cancer invasion and metastasis by inducing the expression of adhesion molecules, such as intercellular adhesion molecule-1 (ICAM-1) and vascular cell adhesion molecule-1 (VCAM-1), and metalloproteinases (MMPs)." (PMID 30166456, 2018). "The cell adhesion molecules (CAMs), such as vascular cell adhesion molecule-1 (VCAM-1), intercellular adhesion molecule-1 (ICAM-1) and endothelial cell selectin (E-selectin), which expressed by endothelial cells may play a critical role in the cancer metastasis." (PMID 25823660, 2015). "The overall effects of exercise on circulating ICAM-1, VCAM-1, and MCP-1 in cancer patients were small and nonsignificant." (PMID 41583457, 2025).
cancer (continued). "They found that, four days after cisplatin injection with no cancer cells, the expression of VEGFR-1 is up-regulated in the activated (VCAM1+) endothelial cells." (PMID 30373101, 2018). "The basal expression of selected cell surface markers (M1, M2, inhibitory) on either human monocytes or cancer cell lines suggest that human monocytes do not express PDL2 (M2/inhibitory), VCAM-1 (M1), CD206 (M2), and have a low expression of PDL1 (M1/inhibitory) and CD163 (M2) (black lines)." (PMID 29668679, 2018). "Therefore, although we have not yet determined the precise role of ICAM-1 and VCAM-1 expression in CRC cells, ICAM-1 and VCAM-1 in the resistin-treated cancer and endothelial cells may be secreted into the cancer microenvironment and mediate the interactions of cancer, immune, and endothelial cells." (PMID 26690142, 2015).
infection (150 papers, 2006 to 2026). The state of being infected such as from the introduction of a foreign agent such as serum, vaccine, antigenic substance or organism. "The usual role of VCAM-1 is to promote transendothelial migration of leukocytes into areas of infection but in vascular pathologies, VCAM-1 can cause an inflammatory mesh, ensnaring leukocytes, consuming coagulating factors and causing pathological complement and platelet activation." (PMID 40497429, 2025). "Indeed, in vitro studies have shown upregulation of ICAM-1 and VCAM-1 expression in human endothelial cells upon infection with myocarditis-associated viruses (adenovirus, arenavirus, coxsackievirus B3 (CVB3), cytomegalovirus, and West Nile virus) or upon infection with T. cruzi." (PMID 29536322, 2018). "Therefore, we cannot exclude the possibility that the failure to overcome VCAM-1 blockade resulted from altered DC trafficking caused by infection or the fact that DC from infected mice are unable to traffic effectively back to the T cell zones within the spleen." (PMID 18802456, 2008). "VCAM-1 is a cell adhesion molecule that plays a critical role in inflammatory responses, specifically involved in leukocyte emigration to infection sites." (PMID 40231172, 2025). "Previously, an increase in the expression of VCAM-1 was described as a result of experimental infection in cell cultures by T. cruzi." (PMID 40623042, 2025). "Neutrophilia, low MHCII expression by monocytes, and elevated plasma Resistin, IL-6, myoglobin, and VCAM-1 correlated with fatal infections." (PMID 37598150, 2023). "MPO and VCAM-1 were also positively correlated with Hispanic ethnicity in this group, and myoglobin was significantly elevated in fatal infection." (PMID 37598150, 2023). "It is unclear why MAdCAM-1 is superior to either VCAM-1 or CD28 Ab with respect to supporting infection." (PMID 36897929, 2023). "Our analysis showed that ΔsteE STm infection led to lower frequencies of RPM, Nos2+, Vcam1+, and Trem2+ MΦs compared to WT STm infection." (PMID 36608122, 2023). "The severe infection group demonstrated significantly elevated circulating levels of myoglobin, VCAM-1, and MPO which were significantly correlated with severe infection." (PMID 37598150, 2023). "In return, these cells exhibited a massive release of von Willebrand factor (vWF) within two hours post-infection as well as vascular cell adhesion molecule-1 (VCAM-1), which is an another platelet adhesion protein." (PMID 36768333, 2023). "VCAM‐1/VLA‐4 antibody blockade inhibits monocyte recruitment to the brain vasculature during infection." (PMID 37452512, 2023). "The results showed that compared with ANRIL overexpression, the Sh-ANRIL double infection increased the expression of eNOS, decreased the expression of VCAM-1 and vWF." (PMID 35906216, 2022). "Further, the combination including four validated indexes and two classical infection indexes for septic diagnosis had the highest AUC‐ROC of 0.772, which was significantly better than that of ApoC3, VCAM1, and ApoE respectively, besides B2M." (PMID 34825737, 2022). "VCAM-1 is a monocyte endothelial ligand that mediates monocytes’ recruitment from the bloodstream to sites of infection and injury." (PMID 36139488, 2022). "Accordingly, in a murine model of H1N1 infection, treatment with 1,8-cineole inhibited the upregulation of ICAM-1 and VCAM-1 induced by infection, corroborating the anti-inflammatory effect of the compound." (PMID 35550638, 2022). "During the lung stage of infection, schistosomula remain in vasculature by suppressing immune activation of lung endothelial cells via targeting of integrins, E-selectin, and Vcam1." (PMID 35295754, 2022). "At the same time, studies have shown that the use of genetic engineering to extract the cell membrane which overexpressed vascular cell adhesion molecule-1 (VCAM-1) can adhere to the inflammation site and recruit immune cells to fight the infection." (PMID 36384635, 2022).
infection (continued). "Adhesion molecules such as VCAM-1 play a role in inflammation by facilitating the adhesion of leukocytes at the site of infection to help regulate inflammation and stimulate tissue healing." (PMID 34502403, 2021). "Western blotting confirmed the increase in adhesion molecules on endothelial cells following infection, including VCAM-1, ICAM-2, E-selectin, VE-cadherin, and beta-catenin." (PMID 34532298, 2021). "Vcam1 staining was restricted to the brain vasculature, and the staining results showed that abundances increased during infection with both strains used in this study." (PMID 32843537, 2020). "Blood vessels in lungs harvested after 45 days of infection were stained to quantify the presence of vascular cell adhesion molecule (VCAM)-1 via immunohistochemistry." (PMID 33312173, 2020). "We previously found that MAIR‐II expressed on inflammatory monocytes regulates lipopolysaccharide‐TLR4–mediated cell adhesion to vascular cell adhesion molecule 1, promoting monocyte migration to sites of infection." (PMID 33140535, 2020). "The release of HMGB1 also increases the expression of ICAM-1, VCAM-1 and pro-inflammatory cytokines in endothelial cells, suggesting a propagation of the immune response during infection or injury by HMGB149." (PMID 31748599, 2019). "Cell adhesion molecules such as Vcam1 and Icam1 play a role in leukocyte migration to the site of infection." (PMID 31166414, 2019). "Overall, lower expression of IL17, IL22, PTX3, and heterophil attracting cytokines, such as CXCL8 and VCAM1 in our data suggests a dampened innate immune response post APEC O2-GFP infection." (PMID 31998322, 2019). "While expression of P-selectin, ICAM-1, and VCAM-1 were increased in infected WT mice, the expression of these molecules was unchanged by the infection in Gas6−/− mice." (PMID 29967614, 2018). "As Fig. 1Aii shows, at a lower bacterial dose of 106 cfu ml−1, the WT bacteria induced low level expression of both E‐selection and VCAM‐1, whereas infection with the lpxA‐ bacteria mediated minimal effect on both adhesion molecules expression." (PMID 26153406, 2016). "Expression of VCAM-1 gene was shown in porcine choroid plexus epithelial cells activated by S. suis and in different tissues after in vivo infection." (PMID 24708855, 2014). "In fact, focused heat maps revealed that no innate immune genes were up- or down-regulated in IFNR−/− mice at day 15 or 140 post-infection besides VCAM1 and CCL21b." (PMID 23737750, 2013). "Accumulation of leukocytes at the site of local injury or infection of endothelial cells is dependent on the interaction of circulating leukocytes with vascular adhesion molecules, such as E-selectin, VCAM-1, and ICAM-1." (PMID 23209478, 2012). "In vivo approaches also showed that the inhibition of AEA uptake reduced the expression of brain VCAM-1 in response to TMEV infection." (PMID 21851608, 2011). "In the present study we investigated the effects of anandamide (AEA) in the regulation of VCAM-1 expression induced by Theiler's virus (TMEV) infection of brain endothelial cells using in vitro and in vivo approaches." (PMID 21851608, 2011). "E-selectin and VCAM-1 expressions increased by ∼100% due to infection, and ICAM-1 expression showed a moderate increase." (PMID 21249123, 2011). "In arthritic joints of SCID mice infected with B. burgdorferi, Schaible and coworkers observed the appearance of PNAd only late during infection following early upregulation of other adhesion molecules such as P-selectin, VCAM-1 and ICAM-1." (PMID 16772045, 2006). "Additionally, it suppresses the expression of MHC-II molecules and adhesion molecules (ICAM-1 and VCAM-1), which impairs antigen delivery, hinders the immune system’s clearance of S. suis, and facilitates the establishment of a persistent infection." (PMID 41304154, 2025).
infection (continued). "According to vascular mechanisms, an increased expression of miR-126 may be associated with the alleviation of inflammation and decreased cell recognition and infection by the virus as it targets VCAM-1." (PMID 39456716, 2024). "These interactions are facilitated via cellar adhesion molecules such as Intercellular Adhesion Molceulse-1 (ICAM-1) and Vascular cell adhesion molecule-1 (VCAM-1) present on the surface of endothelial cells, resulting in the infiltration of leukocytes to the site of infection." (PMID 38254684, 2024). "TNF signaling also stimulates the production of adhesion molecules, such as intercellular adhesion molecule-1 (ICAM-1) and vascular cell adhesion molecule-1 (VCAM-1), which allow immune cells to adhere to and traverse the endothelial barrier to reach the site of infection." (PMID 37511508, 2023). "Endothelial cells respond to C. albicans infection by expressing adhesion molecules, such as intercellular adhesion molecule-1 (ICAM-1) and vascular cell adhesion molecule-1 (VCAM-1), which promote the binding and migration of leukocytes to the site of infection." (PMID 37511508, 2023). "Also important in immune cell recruitment, selectins (Selp, Sele) and adhesion molecules (Vcam1) were significantly upregulated in BECs with infection, while tight junction molecules like Cldn5 were downregulated." (PMID 35789215, 2022). "Additionally, fluticasone propionate is more potent in suppressing vascular cell adhesion molecule-1 expression in bronchial epithelial cells, leading to the inhibition of leukocyte recruitment to infection sites." (PMID 35887686, 2022). "The first study chronicling a functional EMCV receptor reported that infection of primary vascular endothelial cells by the EMC-D strain was inhibited by antibodies targeting vascular cell adhesion molecule 1 (VCAM-1), a protein belonging to the immunoglobulin superfamily." (PMID 31409686, 2019). "VCAM1 is a gene important for lymphocyte extravasation to sites of infection." (PMID 28100256, 2017). "During the initial stages of infection, such as in IE, the toxin may be produced at low concentrations, therefore inhibiting the production of IL-8 and VCAM-1, to delay activation of the host immune system until colonization is established." (PMID 28325766, 2017). "However, increases in VCAM-1, induced by PbA infection were only partially reversed by BQ123 treatment (1.10 ± 0.07 in PbA+BQ123 vs. 1.33 ± 0.1 in PbA; P = 0.066)." (PMID 27031954, 2016). "Similarly, endobronchial mucosal biopsies and bronchoalveolar lavage fluid from HFRS patients revealed activated CD8+ T cells and strong upregulation of vascular cell adhesion molecule 1 (VCAM-1) at the site of infection." (PMID 25859243, 2015). "Costimulatory molecules (CD80, CD86, CD40, GITR, and ICOS), adhesion molecules (VCAM-1 and P-selectin), and signaling molecules involved in cytokine regulation (Tbx21 and Socs1) were also increased with Hb infection and decreased with anti-IL-7Rα M595 treatment in a dose-dependent manner." (PMID 23057802, 2012). "Similarly, IL-5 (β = -0.5, p = 0.001) and VCAM-1 levels (β = -0.603, p = 0.009) were significantly decreased by the interaction, suggesting that coinfection can substantially alter the inflammatory response compared to individual infections." (PMID 39093864, 2024). "Moreover, miR-126-mediated downregulation of VCAM-1 may cease positive feedback, which exacerbates infection by allowing viruses to recognize and enter cardiac cells via adhesion molecules." (PMID 39456716, 2024). "The experiments in porcine reproductive and respiratory syndrome virus (PRRSV) natural infection and experimental infection of porcine lung injury model showed that the combined expression of VCAM-1 and IL-8 may be a biomarker of viral infection induced lung injury." (PMID 36110525, 2022).